EPHA2 (EPH receptor A2)
Diseases named in the same sentence as EPHA2 in open-access papers (continued):
Sharing a sentence is not in itself a finding about the gene and the disease.
tumor (continued). "Immunohistochemical analyses have identified EphA2 expression in Her-2 and TNBC subtypes, establishing its correlation with clinical parameters, such as tumor grade, stage, and patient survival." (PMID 38612592, 2024). "In summary, this study reveals differential activation of salvage angiogenic pathways in surgical specimens, with FGF2, EphA2, and PLGF upregulated in tumor vessels, while ANGPT1 and ANGPT2 were downregulated and upregulated, respectively." (PMID 38619734, 2024). "In order to evaluate the role of EphA2 in tumor VM formation in vivo, we used MHCC97-H/EphA2 OE and MHCC97-H/EphA2 KD cells to construct xenograft tumor models." (PMID 39050762, 2024). "The tumor growth was increased by EphA2 depletion while it was decreased by RNF5 depletion, and double depletion exhibited slightly slow growth compared with control tumor growth." (PMID 37816703, 2023). "The potential regulatory mechanism is associated with some critical signaling molecules involved in tumor metastasis, invasion, and matrix reconstruction, such as vascular endothelial cadherin (VE‐cadherin), VEGFA, EphA2, PI3K/AKT signals, MMPs, and HIF‐1α." (PMID 36708044, 2023). "The ADC 1C1-maleimidocaproyl-MMAF (mcMMAF) triggered apoptosis of EphA2-expressing cells with an IC50 value of 3 ng/mL and suppressed tumour development in vivo." (PMID 36830852, 2023). "Hypoxia has been reported to promote VM in a wide variety of tumor cell lines through the upregulation of genes such as VEGF-A, VEGFR-1, EphA2, Twist, Nodal, COX-2, and VE-cadherin." (PMID 37298296, 2023). "To further confirm the tumor-suppressive function of EphA2 induced by RNF5 inhibition, we established single or double RNF5- and/or EphA2-knockdown MCF7 cells and injected them into BALB/c nude mice to detect the xenograft tumor growth." (PMID 37816703, 2023). "One study found that EphA2 targeting siRNA-DOPC, significantly reduced tumor growth compared to control siRNA in SKOV3 mice (0.35 vs. 0.70 g; p = 0.020)." (PMID 37612696, 2023). "While there have been substantial advances in the clinical effectiveness of EphA2 redirected CAR-T cells for GBM, the anti-tumour effects of CAR-T cells generated in different labs or by different methods remain uneven." (PMID 37304305, 2023). "Frequently upregulated MAPK pathway genes in resistant tumours were apart from DUSP6 different FGFs, MYC, EPHA2, and FOS." (PMID 37604687, 2023). "The tumor weights were similarly affected by transduction of EphA2 shRNA alone or RNF5 siRNA alone, and the double transduction abolished their effect and generated the approximately equal tumor weights compared with the control group." (PMID 37816703, 2023). "EphA2 is highly expressed in many KRAS-mutant LC cells and has been shown to regulate tumor malignancy." (PMID 37370855, 2023). "The T cells can generate CARs that target antigens universally expressed by tumors, like EphA2 and IL13R2, after being primed by a highly tumor-specific neoantigen, like EGFRvIII, and being trained to carry out complete tumor destruction." (PMID 36604431, 2023). "For example, the tumor-specific antigen EGFRvIII is activated by the SynNotch receptor to induce local CAR expression, which is then coupled with EphA2 and IL13Rα2 to induce tumor cell recognition and killing." (PMID 36707873, 2023). "However, the regulation of EphA2 tumor-suppressive function remains unclear." (PMID 37816703, 2023). "Therefore, our results indicate that RNF5 inhibition could switch EphA2 from tumor-promoting to tumor-suppressive functions by promoting its stability and cell-surface distribution, inducing the unbalance of EphA2 phosphorylation and then decreasing ERK-MAPK activation." (PMID 37816703, 2023). "Overall, they suggested that miR-520e plays a role in the regulation of HBV replication by inhibiting the p38MAPK and ERK1/2 signaling pathways through an inhibitory effect on EPHA2, ultimately reducing HBV replication and inhibiting tumor cell growth." (PMID 37444544, 2023).
tumor (continued). "Small molecules aiming at the G-H loop of EFNA1 and the ligand binding domain of EPHA2, such as lithocholic acid and the SWL peptide, have also been screened but remained to be tested for tumor treatment." (PMID 37160815, 2023). "To investigate a putative signaling link between EphA2 and ADAM17-mediated tumor cell migration, we first determined the phosphorylation status of EphA2 S897 after pharmaceutical inhibition of ADAM17 activity." (PMID 36998455, 2023). "We also proved EPHA2 is an important new target of DUSP1 and EPHA2 also plays an important role on tumor growth of EC." (PMID 37057290, 2023). "However, loss or decrease of antigen in tumor cells has become the main obstacles for EGFRvIII’s further study, and overlapping of the antigen expression on normal tissues has caused off-target side-effects in patients receiving CAR-T cells targeting IL13Rα2 and EphA2." (PMID 37481592, 2023). "In a K-Ras mutant mouse model, knockout (KO) of EphA2 increased the number of CD8+ and CD4+ T-cells in tumours, while decreasing the number of immunosuppressive MDSCs and TAMs." (PMID 36830852, 2023). "A phase 1 study examined the side effects and best dose of DOPC-encapsulated EphA2 siRNA in the treatment of patients with metastatic solid tumors or recurrent GBM and demonstrated that this compound is able to slow the growth of tumor cells (NCT01591356)." (PMID 37071295, 2023). "EPHA2, when overexpressed, activates the mTORC1 and ERK pathways independently of ligands, promoting tumor growth and metastasis." (PMID 37444544, 2023). "We then performed RNA sequencing to profile transcriptome of the four tumor foci and noticed that KLF5 was also the top 1 transcription factor correlated with EPHA2 in the four samples." (PMID 35105853, 2022). "Clinical resection of tumour tissues with VM structures from HCC patients expressed higher EphA2 than VM structure-free tissues, while blocking EphA2 by COE resulted in decreased cell invasion and damaged VM formation." (PMID 35185591, 2022). "Other genes, such as ETV4, ETV5, CCND1, EPHA2, and EPHA4, also play a role in activating the MAPK pathway, promoting tumor resistance to MEKi." (PMID 36437939, 2022). "In the study, we used four tumor foci from a multifocal GBM patient to examine the regulation and function of EPHA2." (PMID 35105853, 2022). "Furthermore, blocking Wnt5a and EphA2 activity with the two agents in combination, not only reduced tumorigenicity and invasiveness, in vivo, addictively but also prevented the recurrence of the tumor upon suspension of their intracerebral infusion after 14 days." (PMID 35414102, 2022). "Blood lakes were found in most EWS tumor samples, and these tumor cells expressed CD44, TFPI-1 and EphA2." (PMID 35354905, 2022). "A Western blot analysis of the removed tumor tissue showed that the expression of CXCL11 and PD-L1 decreased synchronously after EphA2 was knocked down." (PMID 36478746, 2022). "VE-cadherin (***P < 0.001, **P < 0.01) and EphA2 (***P < 0.001, ***P < 0.001) expression was also heightened in ACE2 high expressing and ACEI disposed allograft tumor tissues." (PMID 34221978, 2021). "Therefore, in the context of bone cell–tumor cell interactions, we hypothesized that blocking EphA2 will result in a decrease of osteoclast differentiation and activation, thus breaking the vicious cycle and offering an effective means to control bone metastasis." (PMID 33869989, 2021). "The inhibition of EphA2 and IL31RA activity reduced up to 94% of tumor volume in 50% of dogs in the cohort." (PMID 34631854, 2021). "Gene set enrichment analysis (GSEA) indicated that EphA2 expression was positively correlated with the MAPK signaling pathway, which was closely related to tumor metastasis." (PMID 33879771, 2021). "Several preclinical studies used EphA2-directed CAR T cells to treat GBM xenografts and showed potent anti-tumor activity against glioma-initiating cells." (PMID 34884607, 2021).
tumor (continued). "It has previously been shown that EphA2 influences NSCLC cell signaling and has an impact on their response or refractoriness to EGFR-TKI treatment as well as upon targeting tumor cell expressed VEGFR2." (PMID 33671073, 2021). "We next examined the in vitro tumorigenicity of EphA2 using MTT assay, transwell migration assay, wound‐healing assay and tumour sphere formation assay." (PMID 33586348, 2021). "We and others have previously shown that EphA2 controls NSCLC cell survival, cell death, migration and response to EGFR-TKI or VEGFR2-targeting on tumor cells." (PMID 33671073, 2021). "In order to test the antitumoral effect of the EphA2 inhibitor ALW-II-41-27, we generated patient-derived in vitro models, starting with six primary tumor tissues (OS-29, OS-26, ES-7, ES-15, CS-281, and CS-347)." (PMID 34831119, 2021). "Taken together, these findings demonstrate that EphA2-SE plays an oncogenic role and promotes tumor progression in various tumors by recruiting FOSL2 and TCF7L2 to drive the expression of oncogene EphA2." (PMID 33712565, 2021). "The authors used the CNS- or tumor-specific antigens myelin oligodendrocyte glycoprotein (MOG) or EGFRvIII, respectively, as activating signal for the expression of anti-EphA2 or anti-IL13Ra2 CARs." (PMID 34884607, 2021). "It has been evidenced that EphA2 promotes EWS angiogenesis, tumor growth, and metastasis, and that EphA2 CAR-T cells also exhibit antitumor activity in mice." (PMID 34566963, 2021). "Results suggested that EphA2-SE recruits TCF7L2 and FOSL2 through the core component E1 to directly target EphA2 and promote tumor progression in cancer cells." (PMID 33712565, 2021). "Expression patterns in PBTs are mostly heterogenous with some TAAs more robustly expressed across tumor subtypes (GD2, B7-H3, IL13Rα2), while other targets have variable expression frequencies and intensities (HER2, EphA2, EGFRvIII)." (PMID 34760690, 2021). "Further studies observed improved T cell-dependent killing of poorly immunogenic tumor cells by HSP90 inhibition via additional mechanisms involving inactivation of HER2/neu, EphA2, or TCLA1, respectively." (PMID 32984042, 2020). "Various genes such as vascular endothelial cadherin (VE-cadherin) and erythropoietin-producing hepatocellular receptor A2 (EphA2), and signaling pathways including the phosphoinositide 3-kinase/AKT pathway participate in VM formation by aggressive tumor cells." (PMID 31936664, 2020). "4B3, a monoclonal antibody specific to human EphA2, was also labeled with 64Cu and used for PET/magnetic resonance imaging (MRI) in GBM models, demonstrating clear delineation of tumor boundaries." (PMID 32397088, 2020). "EphA2-ILs-DTXp was engineered to have advantageous pharmacokinetic properties, resulting in decreased plasma exposure to DTX while maintaining selective tumor exposure." (PMID 33092175, 2020). "EphA2 promotes RCC invasion and survival and is correlated with RCC grade, tumor size, and poor prognosis." (PMID 33172177, 2020). "It has been reported that EphA2 tyrosine kinase inhibitor, ALW-II-41-2730, has obvious anti-tumor effects in the many types of cancers." (PMID 32848131, 2020). "In TNBC, brucine, a traditional medicinal herb, was reported to inhibit VM formation in a dose-dependent manner, and downregulate the expression of EphA2, MMP-2, and MMP-9, which are key mediators of tumor invasion, metastasis, and VM formation." (PMID 32169087, 2020). "As expected, considering the relationship between EphA2 expression and GBM progression, the inhibition of EphA2 mediated by A40s treatment reduces self-renewal of GSCs and GBM tumor propagation." (PMID 32764266, 2020). "To validate the clinical relevance of our findings, we next assessed RSK, EphA2, and GPRC5A by immunofluorescence in human HGSC tumor tissue sections." (PMID 32115889, 2020).
tumor (continued). "EFNA1 conferred resistance to photofrin-mediated photodynamic therapy resistance in ESCC cells, and EPHA2, which was hyperphosphorylated in ESCC, promoted tumour cell proliferation, migration, invasion and epithelial–mesenchymal transition." (PMID 32732965, 2020). "The humanized EphA2 mAb 1C1, labeled with 64Cu, was used for positron emission tomography (PET) imaging of eight tumor models with different EphA2 expression levels, showing good correlation between tumor uptake and EphA2 expression." (PMID 32397088, 2020). "Combination of EphA2-ILs-DTXp and gemcitabine in one PDX model led to improved tumor growth control compared to monotherapies or the combination of free docetaxel and gemcitabine." (PMID 33092175, 2020). "Particularly, EphA2 overexpression has been observed in vascular regions of GBM, indicating its role in tumor neovascularization." (PMID 32340173, 2020). "In agreement with our mutational assays, impaired S897 phosphorylation could compromise the tumor-promoting activities of EphA2 in cell growth, migration, invasion and, most importantly, sorafenib sensitivity in resistant cells (HuH-7R) relative to control cells overexpressing wild-type EphA2." (PMID 32203105, 2020). "miR-200a is a tumor suppressor that inhibits cell migration in triple negative BC by regulating the E-cadherin and oncogene EPH receptor A2 (EPHA2)." (PMID 31661891, 2019). "In contrast, EphA2 can be activated by interaction with other cell-surface molecules in cancer cells, thus amplifying MAPK, RAS, and AKT signalings, which enhances tumor development." (PMID 30451837, 2018). "Immunohistochemical evaluation of EphA2 showed that this receptor stained U87MG tumor cells and endothelial cells in about 40% of the tumor area (as shown in the low magnification 100x picture, panel a with a SI score of 6)." (PMID 29849945, 2018). "Recent findings have proposed that EphA2 and EphA3 not only sustain the survival of GBM primary lines but also promote the renewal of tumor-propagating cells with stem-like characteristics (TPC)." (PMID 29849945, 2018). "Combined delivery of EphA2 and FAK siRNAs decreased 67–70% of tumor weight compared to EphA2 and FAK (single) treated group." (PMID 29861465, 2018). "The tumor-bearing mice were treated with control siRNA-DOPC, EphA2-siRNA-DOPC, EphA2+FAK-siRNA-DOPC and EphA2+Src-siRNA-DOPC intraperitoneally twice in a week at a dose of 5 μg siRNA/200 μL suspensions." (PMID 29861465, 2018). "ALW treatment also inhibited the cell proliferation and tumor microvessel density (as measured by Ki67 and CD31 staining) in sh-NC AGS tumors, and these inhibition abilities were impaired in sh-EphA2 tumors." (PMID 30451837, 2018). "In an orthotopic lung tumor xenograft model, when human PBMCs were delivered together with the EphA2.TEA-VV, tumor growth was significantly reduced compared to mice receiving only oncolytic VV or unarmed oncolytic VV with PBMCs." (PMID 30298067, 2018). "Western blotting confirmed that cells from control tumours expressed both EphA2 and RCP protein, and that genetic disruption of the EPHA2 and RCP genes led to disappearance of their protein products." (PMID 28294115, 2017). "Immunohistochemical analysis of the tissue micro array derived from these patients established the functional correlation between the decreased expression of tumor suppressive miRNAs and their target oncogenes: ERBB2, EGFR, EPHA2, BAX, GNA12, GNA13, and JUN." (PMID 28740575, 2017). "In this study, we evaluate the expression patterns of EphA2 and EphB4 by immunohistochemical (IHC) staining of a tissue microarray (TMA) consisting of pairs of tumor and normal colon tissue." (PMID 28165374, 2017). "We have previously shown that a soluble form of eA1 ligand is still active in inducing EphA2 down-regulation and thus in reducing the oncogenic potential of GBM tumor cells." (PMID 27494882, 2016).
tumor (continued). "Mice received 1 × 107 CD19-ENG T cells or EphA2-ENG T cells i.v. with one i.p. dose of 1500 IU IL2 on days 7, 14, and 21 post tumor cell injection." (PMID 27255991, 2016). "This is evident also for EphA2 which is reported to drive tumor invasion and proliferation in NSCLC and other tumor types." (PMID 27533087, 2016). "Having established that EphA3 and EphA2 together are promising molecular targets in GBM tumor cells, tumor neovasculature (EphA2), tumor-initiating and tumor-infiltrating cells of monocytic origin, we focused on combinatorial targeting of these receptors." (PMID 27494882, 2016). "On day 14 post tumor cell injection, mice received 3 × 106 eGFP.ffLuc-expressing CD19-ENG or EphA2-ENG T cells." (PMID 27255991, 2016). "CD19-ENG or EphA2-ENG T cells homed to tumor sites, and CD19-ENG T cells proliferated immediately in contrast to EphA2-ENG T cells as judged by bioluminescence imagining, indicative of antigen-dependent T-cell expansion." (PMID 27255991, 2016). "Collectively, these results suggest functional correlation between the serine phosphorylation of EphA2 and the activation of RSK in human tumour microenvironments." (PMID 26158630, 2015). "Many molecule mechanisms, especially VE-cadherin, EphA2, PI3K, MMPs, VEGFR1 and HIF-1a, are involved in tumour migration, invasion, and VM formation." (PMID 25598425, 2015). "Our results suggest that two circulating peptides derived from C3f, a substrate of MMP-9 in the tumor microenvironment, reflect the content of MMP-9 in tumors, and consequently indicate the therapeutic efficacy (i.e., treatment with EphA2-siRNA)." (PMID 25788424, 2015). "Multivariate analysis was applied using the Cox proportional hazards model with the prediction factors of tumor size, TNM classification, lymph node metastasis and the expression of EphA2." (PMID 25013485, 2014). "Over-expression of EPHA2 in tandem with a diminished engagement with the EFNA1 ligand can lead to increased motility and invasive properties of tumor cells which is consistent with a pro-metastatic phenotype." (PMID 25025847, 2014). "ANXA1 protein was detected in 81 % (97/120) of tumours, CAV-1 in 44 % (54/122) of tumours and EphA2 in 74 % (90/121) of tumours." (PMID 25594008, 2014). "An abnormal expression of EPHA1, EPHA2 and EFNA1 with influence on patient outcome has been demonstrated in different tumor entities." (PMID 25025847, 2014). "The main differences observed between the two types of hypoxia involved the expression of several genes such as IL-8, CXCL2, EPHA2, AREG, HBEGF, and PLAU, which are relevant to tumor progression." (PMID 25122487, 2014). "Thirty one % (35/113) of tumours tested expressed all three markers and 19 % (21/112) had moderate or strong expression of ANXA1, CAV-1 and EphA2." (PMID 25594008, 2014). "Defining the role of EphA2 and ephrin-A1 in NSCLC is particularly important, as EphA2 receptor is highly expressed in NSCLC which contributes to tumor development." (PMID 22824143, 2012). "Therefore, targeting EphA2 may have direct anti-tumor and ant vascular effects." (PMID 19949545, 2009). "Substantial tumor growth inhibition, and complete remission without severe toxicity (6 of 18 mice), was observed in HT-1080 xenograft mice after [177Lu]Lu-EphA2 mAb (3 and 10 MBq) administration." (PMID 39934299, 2025). "Furthermore, PET imaging and therapeutic agents targeting pan-tumor molecules such as LAT1, GPC-1, and EphA2 have already been developed and are currently undergoing optimization for clinical translation." (PMID 40717183, 2025). "Therefore, in the present study, we aimed to directly evaluate the oncogenic role of EphA2 using shRNA-mediated knockdown in a syngeneic RCC model, thereby preserving tumor–immune interactions and enabling longitudinal in vivo monitoring." (PMID 41440001, 2025). "The presence and absence of EphA2 and ephrinA1 expression in AdCC tumor cells respectively was observed by immunohistochemical analysis." (PMID 40421081, 2025).